GLP1R (glucagon like peptide 1 receptor)
Diseases named in the same sentence as GLP1R in open-access papers (continued):
Sharing a sentence is not in itself a finding about the gene and the disease.
type 2 diabetes (continued). "Similar to the sodium-glucose cotransporter 2 (SGLT2) inhibitors, some glucagon-like peptide-1 receptor agonists (GLP-1RAs) have also demonstrated a marked risk reduction in major adverse CV events (MACE) in patients with type 2 diabetes at high risk of CV events." (PMID 29895290, 2018). "This case-controlled study investigated whether polymorphisms in the GLP-1R gene affect the risk of cardiovascular disease in type 2 diabetic patients in the Chinese Han population." (PMID 30271789, 2018). "In efforts aimed at identifying coding variants that underlie susceptibility for developing type 2 diabetes mellitus, an A316T substitution in the GLP-1R was found to associate with lower fasting blood glucose concentrations but higher glucose levels 2 h following a glucose challenge." (PMID 26975372, 2016). "Furthermore, reduced islet GLP1R levels associate with lower insulin secretion, which is seen in patients with type 2 diabetes." (PMID 23879380, 2013). "A retrospective study found that the use of GLP1R agonists was associated with lower risk for 10 of the 13 obesity-associated cancers in type 2 diabetes patients although the mechanisms remain unclear, suggesting a need for further preclinical and clinical investigation." (PMID 40094000, 2025). "Glucagon-like peptide-1 receptor agonists (GLP-1RAs) are medications for managing type 2 diabetes (T2DM) and weight loss." (PMID 40471297, 2025). "Glucagon-like peptide-1 receptor agonist (GLP-1RA) is widely used in the treatment of type 2 diabetes mellitus (T2DM) for its significant hypoglycemic effect, weight loss and small side effects." (PMID 39465848, 2024). "Glucagon‐like peptide‐1 receptor (GLP‐1R) agonists induce weight loss in patients with type 2 diabetes mellitus (T2DM), but the underlying mechanism is unclear." (PMID 38965822, 2024). "Glucagon-like peptide-1 receptor agonist (GLP-1RA) medications are frequently prescribed for the treatment of type 2 diabetes mellitus (T2DM) and for weight loss in overweight or obese patients with or without T2DM1." (PMID 36723995, 2023). "Obesity is highly associated with type 2 diabetes mellitus (T2DM), both of which can be simultaneously treated with glucagon-like peptide-1 receptor agonists (GLP-1RAs)." (PMID 37456411, 2023). "The glucagon-like peptide 1 receptor rs3765467 polymorphism was significantly associated with age at type 2 diabetes diagnosis and thus may be used as a marker to screen and detect individuals at risk of developing early onset type 2 diabetes." (PMID 38131033, 2023). "Semaglutide is a glucagon-like peptide 1 receptor agonist that improves glycemic control and achieves weight loss in type 2 diabetes (T2D) patients." (PMID 37955013, 2023). "In fact, a variant in the GLP1R gene (rs6923761; p.Gly168Ser) was found to be associated with a smaller reduction in HbA1c (by 3.0 mmol/mol [0.27%] per A allele) in individuals with type 2 diabetes treated with sitagliptin, vildagliptin or linagliptin for 6 months." (PMID 33594477, 2021). "This cohort study of older adults with type 2 diabetes examines the association of incident fracture with initiating a sodium-glucose cotransporter–2 inhibitor compared with initiating a dipeptidyl peptidase 4 inhibitor or a glucagon-like peptide 1 receptor agonist." (PMID 34705014, 2021). "Glucagon-like peptide-1 receptor agonists, originally developed for managing type 2 diabetes, have gained attention for their weight-reducing and broader biological effects." (PMID 41129073, 2026). "The aim of this narrative review is to critically assess the renoprotective effects of glucagon-like peptide-1 receptor agonists (GLP-1RAs) in managing albuminuria among patients with type 2 diabetes mellitus within the framework of personalized medicine." (PMID 41745389, 2026). "Glucagon-like peptide-1 receptor agonists (GLP-1RAs) are incretin-based agents used in the management of type 2 diabetes mellitus (T2DM) and obesity." (PMID 41822624, 2026).
type 2 diabetes (continued). "When co-activated with GLP-1R, NPY2R induces greater weight loss, improves insulin sensitivity and restores beta cell function in mouse models of obesity/type 2 diabetes." (PMID 41094027, 2026). "Glucagon-like peptide-1 receptor agonists (GLP-1RAs) are emerging as a cornerstone in the management of type 2 diabetes and obesity." (PMID 41700259, 2026). "Glucagon-like peptide-1 receptor agonists (GLP-1RAs) have become an essential drug class for treating type 2 diabetes, offering proven benefits in glycemic control, weight reduction, and cardiovascular and renal protection." (PMID 41542765, 2026). "Glucagon-like peptide-1 receptor agonists (GLP-1RAs) are widely used for obesity and type 2 diabetes, yet substantial variability in weight-loss response remains poorly understood." (PMID 42311474, 2026). "The clinical indications for Glucagon-like peptide 1 receptor agonists (GLP-1 receptor agonists) include type 2 diabetes and obesity." (PMID 41583363, 2026). "Manufactured by Novo Nordisk, semaglutide is the newest in a family of glucagon-like peptide-1 receptor agonists used most commonly to treat type II diabetes." (PMID 39848681, 2026). "Background/Objectives: Glucagon-like peptide-1 receptor agonists (GLP-1 RAs) have transformed type 2 diabetes mellitus (T2DM) and obesity care, with clinical trials demonstrating weight loss exceeding 15%." (PMID 42280404, 2026). "Glucagon-like-peptide-1 receptor (GLP-1R) agonists are under development as new drugs to treat type 2 diabetes, liver disease, obesity and cardiovascular diseases." (PMID 42076099, 2026). "BACKGROUND: Oral semaglutide, a glucagon-like peptide-1 receptor agonist (GLP-1 RA), has been shown to reduce major adverse cardiovascular events (MACE) in high-risk individuals with type 2 diabetes in the SOUL trial." (PMID 42169198, 2026). "In August of 2025, Wang and colleagues published a systematic review and meta-analysis quantifying the effects of glucagon-like peptide-1 receptor agonist (GLP1RA) drugs on skeletal muscle mass in patients with type 2 diabetes mellitus." (PMID 41559806, 2026). "Glucagon-like peptide-1 receptor agonists (GLP-1 RAs) have been shown to reduce morbidity and mortality associated with type II diabetes mellitus, and/or obesity, and/or cardiovascular disease in multiple clinical trials." (PMID 41893369, 2026). "Glucagon-like peptide-1 receptor agonists (GLP1RAs) are widely used for the management of type 2 diabetes (T2D) and obesity, yet their safety profile in liver transplant recipients remains insufficiently characterized." (PMID 42291858, 2026). "Since tirzepatide and other GLP-1R agonists already have clinical approval for type 2 diabetes and obesity, a solid foundation exists for further AUD investigation." (PMID 41506148, 2026). "Glucagon-like peptide-1 receptor agonists (GLP-1RAs) have transformed the management of type 2 diabetes and obesity, yet their actions extend beyond glycemic control and weight loss." (PMID 41898712, 2026). "Glucagon-like peptide-1 receptor agonists (GLP-1RAs) are increasingly prescribed for type 2 diabetes mellitus and weight management, with growing off-label use in young adults." (PMID 41646548, 2026). "The glucagon-like peptide-1 receptor (GLP-1R) is a class B1 G protein-coupled receptor (GPCR) that is well established as a treatment target for type 2 diabetes (T2D), obesity, and related metabolic diseases." (PMID 41391570, 2026). "As a result, agents such as glucagon-like peptide 1 receptor agonists, originally developed for the treatment of type 2 diabetes and obesity, are now being actively investigated for their role in addiction treatment." (PMID 41753300, 2026). "Tirzepatide is a glucose-dependent insulinotropic polypeptide/glucagon-like peptide-1 receptor agonist approved in the United States for the treatment of type 2 diabetes, obesity, and obstructive sleep apnea." (PMID 42006438, 2026).
type 2 diabetes (continued). "Glucagon-like peptide-1 receptor agonists (GLP-1 RAs) are a class of antidiabetic medications recently approved for the management of Type 2 Diabetes Mellitus." (PMID 40806889, 2025). "Glucagon-like peptide-1 receptor agonists (GLP-1 RAs) reduce major adverse cardiovascular events (MACE) in patients with type 2 diabetes (T2D), but heterogeneity exists across cardiovascular outcome trials (CVOTs)." (PMID 40886073, 2025). "GLP-1R is a class B1 GPCR that has emerged as a crucial therapeutic target for type 2 diabetes and obesity treatment." (PMID 40629042, 2025). "Glucagon-like peptide-1 receptor agonists (GLP-1RAs) are widely prescribed for the treatment of type 2 diabetes and, more recently, for obesity and weight-related metabolic conditions." (PMID 41300964, 2025). "It is notable that although we have identified that there is an association with a type 2 diabetes‐associated variant (rs2490026‐C) and a GLO1 eQTL, it is possible this eQTL affects GLP1R given that the same variant was associated with multiple genes." (PMID 39838854, 2025). "Tirzepatide, a dual glucagon-like peptide-1 receptor and gastric inhibitory peptide receptor agonist, is an effective treatment for type 2 diabetes mellitus and obesity, resulting in significant improvements in glycated hemoglobin levels and weight reduction." (PMID 40123805, 2025). "Are glucagon-like peptide-1 receptor agonists (GLP-1 RAs) associated with cardiovascular and kidney outcomes in patients with type 2 diabetes, and do these associations differ by body mass index (BMI)?" (PMID 40920377, 2025). "AIMS: Glucagon-like peptide-1 receptor (GLP-1R) has become one of the most promising ligand-receptor systems to target for type 2 diabetes mellitus (T2DM) treatment." (PMID 41307691, 2025). "In 2019, marketing approval was granted for oral semaglutide, the world’s first glucagon-like peptide-1 receptor agonist (GLP-1RA) approved for the treatment of type 2 diabetes, providing a promising new treatment option for people with diabetes." (PMID 40038239, 2025). "Glucagon-like peptide-1 receptor agonists (GLP-1RAs) are a relatively new class of drugs for treatment of Type 2 Diabetes mellitus (T2DM)." (PMID 40342008, 2025). "Semaglutide is a long-acting glucagon-like peptide 1 receptor (GLP-1R) agonist approved for treating type 2 diabetes and obesity." (PMID 40492139, 2025). "Glucagon-like-peptide-1 receptor (GLP-1R) agonists have become a first-line option for management of type 2 diabetes mellitus, and are now widely used in the management of obesity." (PMID 40724523, 2025). "From a therapeutic perspective, GLP-1R agonists are already approved for the treatment of type 2 diabetes and obesity, with well-established safety and pharmacokinetic profiles in humans." (PMID 40915106, 2025). "Among adults with type 2 diabetes (T2D), is the use of sodium-glucose cotransporter 2 inhibitors (SGLT2Is) associated with higher risk of male external genital infection (MEGI) than glucagon-like peptide-1 receptor agonists (GLP-1RAs)?" (PMID 41021225, 2025). "Glucagon-like peptide-1 receptor agonists (GLP-1RAs) have emerged as a primary first-line treatment for type 2 diabetes." (PMID 40140925, 2025). "Among the emerging therapeutic options, glucagon-like peptide-1 receptor agonists (GLP-1RAs) have shown potential in reducing adverse events in patients with type 2 diabetes and obesity with preserved ejection fraction." (PMID 40142790, 2025). "Glucagon-like peptide 1 receptor agonists (GLP-1 RAs) have emerged as a promising therapeutic option beyond their established role in managing type 2 diabetes mellitus (T2DM) and obesity." (PMID 40699685, 2025). "Background/Objectives: Glucagon-like peptide-1 receptor agonists (GLP-1RAs) have revolutionized the treatment of type 2 diabetes and obesity." (PMID 40426877, 2025). "Glucagon-like peptide-1 receptor agonists (GLP-1 RAs) have seen a growing recommendation in the treatment of type 2 diabetes (T2D)." (PMID 41331950, 2025).
type 2 diabetes (continued). "New medications for type 2 diabetes (T2D) control, such as sodium-glucose cotransporter-2 inhibitors (SGLT2Is) and glucagon-like peptide-1 receptor agonists (GLP-1RAs), have emerged." (PMID 41021225, 2025). "In recent years, there has been a dramatic increase in the popularity and use of glucagon-like peptide-1 receptor agonists (GLP-1 RAs) for the treatment of type 2 diabetes and obesity." (PMID 40706081, 2025). "Management of type 2 diabetes mellitus (T2DM) and weight loss has undergone a transformative shift with the introduction of glucagon-like peptide-1 receptor agonists (GLP-1RAs)." (PMID 40656422, 2025). "Does the efficacy of sodium-glucose cotransporter 2 inhibitors, glucagon-like peptide-1 receptor agonists, and dipeptidyl peptidase 4 inhibitors vary by age and sex among individuals with type 2 diabetes?" (PMID 39899304, 2025). "A case study on GLP-1R demonstrates how structural insights have led to the design of successful drugs for type 2 diabetes and obesity." (PMID 40629042, 2025). "Glucagon-like peptide-1 receptor agonists (GLP-1RAs) are widely used in the treatment of type 2 diabetes and obesity due to their metabolic effects." (PMID 41465832, 2025). "Glucagon-like peptide-1 receptor agonists (GLP-1RAs) are a class of medications used in the treatment of type 2 diabetes mellitus (T2DM) and/or obesity." (PMID 40558305, 2025). "Background/objectives: Glucagon-like peptide-1 receptor agonists (GLP-1RAs) are widely used in treating type 2 diabetes and obesity, offering established metabolic and cardiovascular benefits." (PMID 40422559, 2025). "Liraglutide, a glucagon-like peptide 1 receptor agonist (GLP-1 RA), has a dual indication for treatment of both type 2 diabetes mellitus (T2DM) and weight loss treatment." (PMID 39877802, 2025). "Glucagon-like peptide-1 receptor agonists (GLP-1 RAs) also offer renal benefits for patients with type 2 diabetes." (PMID 41347159, 2025). "GLP-1R agonists have demonstrated significant efficacy in the treatment of type 2 diabetes and obesity." (PMID 40230860, 2025). "Glucagon-like peptide-1 receptor agonists demonstrate growing acceptance as therapeutic agents for both glycemic regulation and weight control in patients with type 2 diabetes and obesity." (PMID 40422559, 2025). "Glucagon-like peptide-1 receptor agonists (GLP-1R agonists) are a class of drugs originally developed for the treatment of type 2 diabetes." (PMID 41018201, 2025). "For example, the GLP-1R (glucagon-like peptide-1 receptor) agonist, an exenatide commonly used to treat type 2 diabetes, has been suggested as a potential therapeutic compound for FRDA." (PMID 41007684, 2025). "Glucagon-like peptide-1 receptor agonists (GLP-1 RAs) are a cornerstone in type 2 diabetes management, improving glucose-stimulated insulin secretion, slowing gastric emptying and reducing blood glucose levels." (PMID 40404820, 2025). "GLP-1R (co)-agonists first emerged as therapeutics for treatment of type 2 diabetes mellitus and have since become an established drug class for improving glycemic control." (PMID 41471111, 2025). "Type 2 diabetes mellitus is a major health burden globally, with increasing use of glucagon-like peptide-1 receptor agonists (GLP-1RAs) such as semaglutide for glycemic control and cardiovascular risk reduction." (PMID 40687404, 2025). "By enhancing insulin secretion, inhibiting glucagon release, delaying gastric emptying, and suppressing appetite, GLP-1R agonists (GLP-1RAs) have demonstrated efficacy in managing type 2 diabetes and obesity." (PMID 41357527, 2025). "Long-term remission, at least temporarily, of type 2 diabetes may occur in individuals who change their lifestyle dramatically, usually related to massive weight loss that is also seen after bariatric/metabolic surgery or after long-term treatment with glucagon-like peptide 1 receptor agonists." (PMID 39678649, 2025).
type 2 diabetes (continued). "Glucagon-like peptide-1 receptor agonists (GLP-IRAs) have become pivotal in the management of type 2 diabetes mellitus (T2DM) [...]." (PMID 40429331, 2025). "Glucagon-like peptide-1 receptor agonists (GLP-1RAs) are widely used for type 2 diabetes and obesity, and emerging evidence suggests potential immunomodulatory effects." (PMID 40917833, 2025). "Glucagon-like peptide-1 receptor agonists (GLP-1RAs) have transformed the management of type 2 diabetes and obesity, and growing evidence suggests potential benefits in dermatologic disease." (PMID 41020015, 2025). "Gastrointestinal side effects such as change in bowel habit are commonly associated with metformin and glucagon-like peptide-1 receptor agonists (GLP-1RAs), both of which are primary treatments for type 2 diabetes." (PMID 39976937, 2025). "Semaglutide is a weekly administered glucagon-like peptide-1 receptor agonist (GLP-1RA) used in the treatment of type 2 diabetes mellitus (T2DM) as well as obesity." (PMID 41302309, 2025). "Incretin analogues, such as GLP-1 receptor (GLP-1R) agonists (including semaglutide and liraglutide, among others) have gained widespread attention due to their success in the treatment of type 2 diabetes mellitus and obesity." (PMID 40517248, 2025). "Glucagon-like peptide-1 receptor agonists (GLP-1 RAs) are commonly used for managing type 2 diabetes and obesity." (PMID 40342457, 2025). "Glucagon-like peptide-1 receptor agonists (GLP-1 RAs) are extensively used in the management of type 2 diabetes mellitus (T2DM) and obesity." (PMID 40847331, 2025). "Glucagon-like peptide-1 receptor agonist (GLP-1RA) use among U.S. adults with type 2 diabetes (T2D) surged to 19.4% by 2022, representing 5.1 million people and quadrupling from 2016 levels." (PMID 40832397, 2025). "This cohort study examines associations of glucagon-like peptide-1 receptor agonist (GLP-1 RA) use with cardiovascular and kidney outcomes across body mass index (BMI) categories in patients with type 2 diabetes." (PMID 40920377, 2025). "More recently, glucagon-like peptide 1 receptor agonists (GLP-1RA) for type 2 diabetes and obesity have been developed and are now being widely used." (PMID 40284198, 2025). "Glucagon-like peptide-1 receptor agonists (GLP-1 RAs) reduce chronic kidney disease progression in people with type 2 diabetes mellitus." (PMID 41444417, 2025). "Glucagon-like peptide-1 receptor agonists (GLP-1RAs) have shown benefits for cardiorenal outcomes in patients with type 2 diabetes mellitus." (PMID 40442813, 2025). "The rapid development of multi-receptor drugs targeting glucagon-like peptide-1 receptor (GLP-1R) is driving significant advancements in the treatment of individuals with type 2 diabetes and obesity." (PMID 39968298, 2025). "Glucagon-like peptide-1 receptor agonists are a class of drugs that mimic a natural incretin hormone released by the intestine after meals, and they are well-suited for treating type 2 diabetes." (PMID 40156058, 2025). "Background/Objectives: Glucagon-like peptide-1 receptor agonists (GLP-1 RAs) have transformed the management of type 2 diabetes mellitus and obesity." (PMID 40807216, 2025). "The first GLP‐1R agonist authorized for type 2 diabetes was exenatide, which was followed by liraglutide and semaglutide." (PMID 40671844, 2025). "Glucagon-like peptide-1 receptor agonists (GLP1RAs) are a class of antidiabetic agents known to reduce cardiovascular events in patients with type II diabetes mellitus (T2DM), overweight, and obese individuals." (PMID 40466245, 2025). "These insulinotropic functions have prompted the development of multiple GLP-1R agonists for treating type 2 diabetes mellitus." (PMID 40699782, 2025). "“Ozempic face” and facial aging have been observed as side effects in many patients after glucagon like peptide 1 receptor agonists (GLP-1RA) therapy for type 2 diabetes mellitus (T2DM) and obesity." (PMID 40498168, 2025).